BMPER (BMP binding endothelial regulator)
Diseases named in the same sentence as BMPER in open-access papers (continued):
Sharing a sentence is not in itself a finding about the gene and the disease.
amyotrophic lateral sclerosis (1 paper, 2014). Amyotrophic lateral sclerosis (ALS) is a neurodegenerative disease characterized by progressive muscular paralysis reflecting degeneration of motor neurons in the primary motor cortex, corticospinal tracts, brainstem and spinal cord. "The most downregulated gene was BMPER, an inhibitor of BMP (-10 fold) followed by NIF3LBP1 (-7.4 fold), which binds NIF3 (an amyotrophic lateral sclerosis candidate gene), MCC1 (-7.4 fold) (a tumor suppressor), and PRLR (-4.2) (a prolactin receptor important for decidua function)." (PMID 26085845, 2014).
Arthritis (1 paper, 2021). Inflammation of a joint. "The G allele for rs17169634 in BMPER has reduced effects on the risk of arthritis (p = 3.76 × 10−6) and prostate cancer (p = 6.32 × 10−3)." (PMID 33657282, 2021). "The BMPER locus was associated with arthritis, prostate cancer, and BMI." (PMID 33657282, 2021). "We further performed association analyses for diseases in dataset 1 and found that the BMPER locus was associated with arthritis (p = 3.76 × 10−6) and prostate cancer (p = 6.32 × 10−3), and the G allele for SNP rs17169634 has decreased effects on the risk of arthritis and prostate cancer." (PMID 33657282, 2021).
autism (1 paper, 2024). Persistent deficits in social interaction and communication and interaction as well as a markedly restricted repertoire of activity and interest as well as repetitive patterns of behavior. "There was a nominally significant set-level association with autism (P = 0.03) that would not remain significant if corrected for multiple testing over all language-related and psychiatric traits, with five genes individually associated at P < 0.05: BMPER, GATB, KCNH5, SNCA, and SYT2." (PMID 39133845, 2024).
Autoimmunity (1 paper, 2022). The occurrence of an immune reaction against the organism's own cells or tissues. "Both NK activation and autoimmunity are linked to BMP signaling, e.g., via an autocrine activation pathway via BMP receptors and BMP ligands in NK cells, which fits our identified target genes BMP1, BMP2, BMP3, BMP7, BMP6, BMPER, BMPR1B, and, most importantly, BMPR2." (PMID 35455956, 2022).
breast carcinoma (1 paper, 2021). "The significant DEGs (CLDN7, BMPER, FGF7, MSRB3) in breast cancer samples compared to normal samples also showed coincident results of significant gene identification." (PMID 34151730, 2021). "Significantly overexpressed genes (CLDN7, MLLT10, RBM33, SH3RF1, SSBP4, and UBE2Z) were correlated with shorter survival, whereas underexpressed genes (BMPER, FGF7, MSRB3, and TNRC6B) were correlated with longer survival in breast cancer." (PMID 34151730, 2021). "The significantly underexpressed genes (BMPER, FGF7, MSRB3, and TNRC6B) in breast cancer were correlated with a longer survival time based on GSE42568 and GSE37751 (P> 0.05), this correlation cannot be demonstrated." (PMID 34151730, 2021).
Cerebral ischemia (1 paper, 2022). Restriction of arterial blood supply to the brain associated with insufficient oxygenation to support the metabolic requirements of the tissue. "Since both systemic and brain BMPER are upregulated by cerebral ischemia, we proposed that the upregulated BMPER has a critical role in pathophysiology of brain ischemia." (PMID 34904361, 2022). "In the present study, we provide the first evidence that BMPER ameliorates cerebral ischemia injury in vivo and in vitro." (PMID 34904361, 2022). "This study elucidates a protective role of BMPER in cerebral ischemia and improves our understanding of the pathophysiological functions of BMPER." (PMID 34904361, 2022). "To ascertain the neuroprotective impact of BMPER against brain ischemia, we tested the effect of recombinant BMPER on primary mouse neurons in an OGD/R model." (PMID 34904361, 2022). "In support of this, we found that the induced activities of caspase‐3 and caspase‐8 upon brain ischemia were partially blocked by BMPER." (PMID 34904361, 2022). "Here, we explored the effects of BMPER on cerebral ischemia and its mechanism of action." (PMID 34904361, 2022). "We also evaluated the changes in brain BMPER levels upon cerebral ischemia." (PMID 34904361, 2022). "All these results highlight a critical role of BMPER in pathophysiology of brain ischemia." (PMID 34904361, 2022). "Brain ischemia significantly upregulated mRNA expression of TNF‐α, IL‐1β, and IL‐6, which were inhibited by BMPER." (PMID 34904361, 2022). "Unlike these BMPs, circulating BMPER levels remained elevated until subacute phase after brain ischemia." (PMID 34904361, 2022).
chronic kidney disease (1 paper, 2021). Impairment of the renal function secondary to chronic kidney damage persisting for three or more months. "BMPER holds a promise for inhibiting the progression of chronic kidney diseases." (PMID 33644047, 2021).
clear cell carcinoma (1 paper, 2020). "The rate of high BMPER expression in clear cell carcinoma was higher than that in other pathological types, but the difference was statistically nonsignificant, probably because of the limited number of samples." (PMID 32309430, 2020). "In terms of pathological types, the rate of high BMPER expression in patients with clear cell carcinoma was higher than that in other pathological types, but it was not statistically significant." (PMID 32309430, 2020).
glioma (1 paper, 2020). A benign or malignant brain and spinal cord tumor that arises from glial cells (astrocytes, oligodendrocytes, ependymal cells). "In summary, in primary high-grade gliomas, BMPER, CXCL10, and HOXA9 expression can promote early-phase tumor growth and further progression by increasing tumor neovascularization." (PMID 32432046, 2020). "In the two glioma surgical specimen groups, the expression levels of BMPER, CXCL10 and HOXA9 in the surgical specimens that could form xenografts were significantly higher than those in the surgical specimens that could not form xenografts." (PMID 32432046, 2020). "We inhibited the expression of BMPER, CXCL10, and HOXA9 using siRNA in the 2 cases of glioma stem cell spheres." (PMID 32432046, 2020). "ROC curve analysis indicated that the scanning parameters rCBV, rCBF, Ktrans, and Vp of the DSC-MRI and DCE-MRI can be used as imaging markers to predict the expression statuses of BMPER, CXCL10, and HOXA9 in tumor tissue, which can guide the antiangiogenic treatment of primary high-grade gliomas." (PMID 32432046, 2020). "Therefore, BMPER, CXCL10, and HOXA9 can be used as novel targets for antiangiogenic treatment of primary high-grade gliomas." (PMID 32432046, 2020). "Transcriptome sequencing results confirmed that the expression levels of BMPER, CXCL10, and HOXA9 in the cases that could form orthotopic xenograft glioma models were significantly higher than those in the cases that could not form xenografts." (PMID 32432046, 2020).
hepatocellular carcinoma (1 paper, 2025). A malignant tumor that arises from hepatocytes. "In hepatocellular carcinoma (HCC), the methyltransferase NSUN6 catalyzes m5C modification of BMPER mRNA, enhancing its stability and elevating BMPER protein expression." (PMID 40589169, 2025).
ischemia (1 paper, 2022). A hypoperfusion of the BLOOD through an organ or tissue caused by a PATHOLOGIC CONSTRICTION or obstruction of its BLOOD VESSELS, or an absence of BLOOD CIRCULATION. "In addition, BMPER significantly reduced the brain water content in the cortex and striatum of MCAO mice, suggesting that BMPER ameliorated brain edema after ischemia." (PMID 34904361, 2022).
ischemic stroke (1 paper, 2022). A stroke disorder caused by obstruction of blood flow to the brain, due to thrombotic (local blood clot formation) or embolic (due to a blood clot or other material traveling from another site) event. "All these findings indicate that BMPER treatment reduces post‐ischemia neuroinflammation after ischemic stroke." (PMID 34904361, 2022). "Therefore, we consider that BMPER may control extrinsic apoptosis but not intrinsic apoptosis in ischemic stroke." (PMID 34904361, 2022).
lymph node metastasis (1 paper, 2020). "High BMPER expression was associated with lymph node metastasis, and the proportion of patients with high BMPER expression in the lymph node metastasis positive group was higher than that in the lymph node metastasis negative group (P < 0.05)." (PMID 32309430, 2020).
lymphoma (1 paper, 2014). A malignant (clonal) proliferation of B- lymphocytes or T- lymphocytes which involves the lymph nodes, bone marrow and/or extranodal sites. "Moreover, the gene BMPER, which encodes for BMP endothelial cell precursor-derived regulator, was frequently methylated in our lymphoma samples." (PMID 25226156, 2014). "Taken together, we identified several genes (BMPER, BMP7, CDH1, DUSP4 and LRP12) which were frequently methylated in major lymphoma types." (PMID 25226156, 2014). "The promoter methylation of LRP12, CDH1, BMPER and DUSP4 was 100%, 91%, 55%, and 32% across all analyzed lymphoma types included in the validation series, respectively." (PMID 25226156, 2014). "The lymphoma patients included in the test series showed methylation frequencies of 93%, 90% and 60% for CDH1, LRP12 and BMPER, respectively." (PMID 25226156, 2014). "For BMPER, CDH1 and LRP12 statistically significant differences in the PMR values were seen between several of the lymphoma groups analyzed, as well as in comparison with the control samples." (PMID 25226156, 2014). "However, to the best of our knowledge, this is the first time BMPER, BMP7, DUSP4 and LRP12 are reported to be methylated in lymphoma." (PMID 25226156, 2014).
mitral valve prolapse (1 paper, 2015). A fairly common and often benign valvular heart disorder characterized by redundancy or hooding of mitral valve leaflets so that they prolapse into the left atrium, often causing mitral regurgitation. "Consistent with the role of the bone morphogenetic protein (BMP) signaling pathway in cardiac valve formation, embryos that are deficient for the BMP regulator BMPER (BMP-binding endothelial regulator) display the cardiac valve anomaly mitral valve prolapse." (PMID 26418455, 2015). "Previous work in the Patterson laboratory identified a cardiac valve anomaly similar to mitral valve prolapse in mice that are homozygous null for the BMP regulator BMPER (BMP-binding endothelial regulator)." (PMID 26418455, 2015).
myocardial infarction (1 paper, 2023). Gross necrosis of the myocardium, as a result of interruption of the blood supply to the area, as in coronary thrombosis. "VCAM-1 supports angiogenesis, EDNRA mediates induction of CDH2 and VEGF by EDN, thereby contributing to tissue restoration after myocardial infarction, while BMPER is known to play an important role in osteogenesis." (PMID 37686058, 2023).
nasopharyngeal carcinoma (1 paper, 2016). A carcinoma arising from the nasopharyngeal epithelium. "In addition, the peptides tested (BMPER, PCDH19, Int β4 and Eps 1) significantly inhibited adhesion of strain WU2 to the D562 nasopharyngeal carcinoma-derived cell line, also widely used in studying the interaction of S. pneumoniae with the host cells." (PMID 26990554, 2016).
ovarian epithelial borderline tumors (1 paper, 2020). "Meanwhile, the rate of positive BMPER expression in ovarian epithelial borderline tumors was higher than that in ovarian epithelial benign tumors and normal ovarian tissues (P < 0.05), and its high expression rate was higher than that in normal ovarian tissues (P < 0.05)." (PMID 32309430, 2020).
ovarian epithelial malignant tumors (1 paper, 2020). "The expression of BMPER was significantly upregulated in ovarian epithelial malignant tumors and was related to increased lymph node metastasis and lower survival rate." (PMID 32309430, 2020).
ovarian epithelial tumor (1 paper, 2020). A benign, borderline, or malignant tumor that originates from the surface epithelium of the ovary. "We aimed to detect BMPER expression in ovarian epithelial tumor tissues and its effects on their biological behaviors, as well as to elucidate the possible mechanism." (PMID 32309430, 2020). "BMPER expression in ovarian epithelial tumor tissues was detected by immunohistochemistry." (PMID 32309430, 2020). "In addition, the immuno-co-staining experiment may be more helpful in determining the type of cells expressing BMPER in epithelial ovarian tumors." (PMID 32309430, 2020).
renal fibrosis (1 paper, 2021). A final common manifestation of a wide variety of chronic kidney diseases characterized by glomerulosclerosis and tubulointerstitial fibrosis. "In this study, by using in vivo unilateral ureteral obstruction (UUO) and in vitro TGF-β1-induced renal fibrosis model, we found that BMPER regulated both tubular dedifferentiation and fibroblast activation, thereby affecting the process of renal fibrosis." (PMID 33644047, 2021). "In view of the inhibitory effects of BMPER on tubular dedifferentiation and fibroblast activation, two essential processes in renal fibrosis, we determined if BMPER could attenuates renal fibrosis in vivo." (PMID 33644047, 2021). "Collectively, exogenous BMPER attenuated renal fibrosis in UUO mice." (PMID 33644047, 2021). "Therefore, we asked if BMPER was involved in renal fibrosis by affecting fibroblast activation." (PMID 33644047, 2021). "Hence, we assumed that BMPER could affect epithelial mesenchymal transition in renal fibrosis induced by UUO mice." (PMID 33644047, 2021). "However, the role of BMPER in renal fibrosis remains unknown." (PMID 33644047, 2021). "Given that E-cadherin down-regulation and fibroblast activation only exist under pathological conditions, BMPER could ameliorate renal fibrosis without affecting constitutive TGF-β1 signaling." (PMID 33644047, 2021). "However, it is not clear whether BMPER is an active player in renal fibrosis." (PMID 33644047, 2021).
Sepsis (1 paper, 2019). Sepsis is defined as life-threatening organ dysfunction caused by a dysregulated host response to infection. "In terms of the important role of endothelial injury and inflammation in sepsis development, BMPER has considerable potential as a novel early diagnostic and prognostic biomarker in infectious diseases." (PMID 30800678, 2019). "For patients with sepsis, BMPER concentrations were increased and associated with CRP, PCT, LAC, and SOFA." (PMID 30800678, 2019).
Stroke (1 paper, 2022). Sudden impairment of blood flow to a part of the brain due to occlusion or rupture of an artery to the brain. "We further confirmed in AIS patients that serum BMPER levels were significantly increased after stroke." (PMID 34904361, 2022).
Ureteral obstruction (1 paper, 2021). Obstruction of the flow of urine through the ureter. "Immunohistochemistry staining showed that 7-day UUO resulted in diminished level of BMPER, especially in dilated and degenerative tubules, which indicated alteration in the kidney microenvironment induced by ureteral obstruction affected its level." (PMID 33644047, 2021). "However, BMPER did not directly improve renal tubular apoptosis and EMT caused by ureteral obstruction." (PMID 33644047, 2021).
urinary tract infection (1 paper, 2019). "Our results suggested that patients with high serum BMPER concentration had high mortality or readmission rate due to febrile urinary tract infection." (PMID 30800678, 2019).
tumor (7 papers, 2014 to 2024). "Whether the role of BMPER in inhibiting tumor cell proliferation is caused by oxidative stress needs further verification." (PMID 38244582, 2024). "Moreover, the bone morphogenetic protein modulator BMPER is highly expressed in malignant tumors and its loss has been shown to impair, among other cellular functions, tumor cell-induced endothelial cell sprout." (PMID 35163822, 2022). "In the late-tumor growth stage, BMPER, CXCL10, and HOXA9 were all lowly expressed, while CD34 was highly expressed." (PMID 32432046, 2020). "Along with further tumor progression, BMPER expression was gradually reduced, while CXCL10 and HOXA9 expression was gradually elevated, which was spatially associated with CD34 expression." (PMID 32432046, 2020). "On day 20 of tumor growth, BMPER was highly expressed, while CXCL10, HOXA9 and the tumor blood vessel marker CD34 were lowly expressed." (PMID 32432046, 2020). "Currently, BMPER has been proven to promote the biological behaviors of some malignant tumor cells, such as lung cancer and colon cancer cells, but the specific mechanism underlying its role in tumors is not completely clear." (PMID 32309430, 2020). "BMPER plays a role in promoting the malignant biological behavior of tumor cells through the MAPK and autophagy-related signaling pathways." (PMID 32309430, 2020). "In our study, tumor growth curves of xenografts were analyzed to confirm that in the early stages of tumorigenesis, BMPER was highly expressed, while CXCL10, HOXA9, and CD34 were lowly expressed." (PMID 32432046, 2020). "The in vivo experiment showed that BMPER was highly expressed in the early tumor growth phase (20 days), CXCL10 and HOXA9 expression was elevated with tumor progress, and spatially associated with tumor vasculature." (PMID 32432046, 2020). "Additionally, changes in tumor growth and progression after inhibiting BMPER, CXCL10, and HOXA9 expression in the xenografts should also be studied." (PMID 32432046, 2020). "Later, BMPER was continuously highly expressed, which significantly increased CD34-positive blood vessels in tumor regions." (PMID 32432046, 2020). "In vitro inhibition of BMPER, CXCL10, or HOXA9 expression reduced the ability of tumor cells to form tube like structure." (PMID 32432046, 2020). "The relationships between BMPER, CXCL10, and HOXA9 expression and the tumor blood vessels were determined in the early- (20, 30, and 40 days) and late-tumor growth stages (80 days)." (PMID 32432046, 2020). "Of these, BMPER mainly played a role in the early-growth phase of tumors, while CXCL10 and HOXA9 mainly played roles in tumor progression." (PMID 32432046, 2020). "In conclusion BMPER, CXCL10, and HOXA9 promote early tumor growth and progression by stimulating neovascularization of primary HGG." (PMID 32432046, 2020).
cancer (3 papers, 2020 to 2023). A tumor composed of atypical neoplastic, often pleomorphic cells that invade other tissues. "BMPER has been reported to be associated with the biological behavior of a few malignant tumors, but the mechanism is still unclear." (PMID 32309430, 2020). "It was an interesting observation that two signaling pathways were identified in our TWM cohort: Ca++ signaling (RYR and TVPM6 mutations) and BMP (BMPER and BRINP2 mutations), which have recently suggested oncogenic functions in other cancer types." (PMID 36980598, 2023). "The results were consistent with previously reported results of BMPER in other cancers." (PMID 32309430, 2020).
BMPER also shares sentences with these, for which no sentence is quoted: lung carcinoma (2 papers); skeletal dysplasia (2); Bardet-Biedl syndrome (1); basal cell carcinoma (1); cardiovascular diseases (1); cervical cancer (1); colon cancer (1); colorectal cancer (1); Glucose intolerance (1); Gorlin syndrome (1); lethal congenital contracture syndrome 2 (1); metabolic syndrome (1); metastatic colorectal cancer (1); nemaline myopathy (1); prostate carcinoma (1); pulmonary arterial hypertension (1); retinopathy (1).